IGF2 (insulin like growth factor 2)
Diseases named in the same sentence as IGF2 in open-access papers (continued):
Sharing a sentence is not in itself a finding about the gene and the disease.
tumor (continued). "These may have improved overall anti-cancer efficiency as they can inhibit the tumor-promoting effects mediated by IGF-2 signaling and hybrid IGF-1R/IR receptors." (PMID 39273251, 2024). "By investigating the transcriptional changes in HB tumor cells on CM-272 exposure, we have detected transcriptional downregulation of the survival factor IGF2 and subsequently reduced activity of PI3K-AKT signaling as the main target of the dual inhibition of UHRF1-driven consequences." (PMID 38285887, 2024). "Further, intratumoral injection of the anti-IGF2 antibody with rHSVQ significantly enhanced survival of DB7 BCBM tumor-bearing mice (median survival of 27 days) compared to anti-IGF2 antibody (median survival of 16.5 days, P < .001) or rHSVQ monotherapy (median survival of 22 days, P = .0041)." (PMID 38853689, 2024). "In addition, we compared the receptor-ligand interaction between C2 IGF2+ tumor cells and other cell types and found that when this subtype interacted with fibroblasts, the ligand receptor had a high communication probability with MDK-NCL." (PMID 39896800, 2024). "IGF2 is reported to play an important role in tumor progression." (PMID 39759028, 2024). "Similarly, histological analysis of brain sections obtained from GBM12 tumor-bearing mice demonstrated a significant increase in IGF2 expression and IGF1R phosphorylation co-localized within the region of active rHSVQ replication." (PMID 38853689, 2024). "In addition, the IGF-Trap has high affinity for IGF2, thereby limiting IGF2/IR-A signaling, which represents a major resistance mechanism activated by tumor cells in response to anti-IGF mAbs or TKIs." (PMID 38892104, 2024). "In the management of IGF2‐mediated hypoglycaemia, particularly in challenging cases of tumour‐induced hypoglycaemia unresponsive to conventional therapies, Pasireotide might be a future option once more evidence in its broader efficacy is available." (PMID 38411039, 2024). "In CRC, LOI of IGF2 can enhance cell autophagy through the PI3K/Akt/mTOR pathway, whereas it might promote tumor formation through the IGF2-INSR pathway in SFT." (PMID 38812777, 2024). "Therefore, it would be intriguing to investigate mechanisms by which oHSV-induced IGF2 modulates the tumor and TME differently in GBM and BCBM tumors." (PMID 38853689, 2024). "Similarly, local anti-IGF2 antibody treatment significantly decreased oHSV therapy-induced recruitment of Ly6G + neutrophils/PMN-MDSCs in DB7 BCBM tumor-bearing mice." (PMID 38853689, 2024). "The tumor-specific interaction may enhance tumorigenesis and metastasis, possibly contributing to the protumor effect of IGF2 in CAFs in vivo." (PMID 39545420, 2024). "Numerous studies have shown that IGF2 is involved in tumor development and metastasis." (PMID 39759028, 2024). "A recent study demonstrated that IGF2 LOI cancer stem cells (CSCs) were generally more prone to tumor formation and had higher levels of autophagy (CD133 with high expression and p62 with low expression) compared with maintenance of imprinting (MOI) cells in patients with CRC." (PMID 38812777, 2024). "The primary driver is the tumours' excessive production of immature and mature IGF‐2 molecules." (PMID 38411039, 2024). "As iCAFs are generally recognized to be tumor promoting via the secretion of inflammatory cytokines, this suggested that IGF2 could have a crucial role in controlling the secretion of cytokines from CAFs." (PMID 39545420, 2024). "In addition, miR-615-3p targeted Insulin like growth factor 2 (IGF2) to inhibit tumor growth and metastasis in non-small cell lung cancer (NSCLC)." (PMID 38257818, 2024). "Interestingly, depleting IGF2 from tumor cells has been described to render them more sensitive to several chemotherapeutic agents." (PMID 38285887, 2024). "Since IGF2 is reported to be responsible for tumor metastasis, and CAFs play key role in metastasis, this drove us to investigate whether IGF2 is involved in CAFs activation." (PMID 39759028, 2024).
tumor (continued). "Protein–protein interaction analysis suggested that IGFBP4 is associated with IGF1, IGF2, and extracellular matrix associated proteins such as COL4A2, which was a significant factor affecting tumor metastasis and implying that IGFBP4 affects cell invasion through the IGF signaling pathway." (PMID 37349627, 2024). "Furthermore, our clinical analysis uncovered a notable positive correlation between IGF2 and PD-L1 in tumor tissues." (PMID 39545420, 2024). "IGF2 could contribute to anti-tumor therapy based on its regulation, modification, and downstream signaling way." (PMID 36512456, 2023). "If no somatic alterations had significant associations the tumor response, overexpression of IGF2 and L1CAM was associated with decreased response." (PMID 36766755, 2023). "Most tumor samples tested showed high IGF-2 protein expression." (PMID 36809604, 2023). "Insulin-like growth factor 2 mRNA-binding proteins (IGF2BPs) serve essential biological functions as post-transcriptional performers, participating in the acquisition or maintenance of tumor hallmarks due to their distinct protein structures." (PMID 37554271, 2023). "However, two previous studies from Japan have assessed the IGF2 methylation status in tumour tissues of CRC patients and the results were inconsistent." (PMID 37213278, 2023). "The elevated level of intracellular Ca2+ induces activation of the insulin-like growth factor 1 receptor (IGF-1R) via release of insulin-like growth factor 2 (IGF2) from airway epithelial cells, which leads to the transformation of the lung epithelial cells and to tumor initiation." (PMID 36835082, 2023). "Other soluble mediators released by epithelial tumor cells, such as β fibroblast growth factor (βFGF) and transforming growth factor β (TGFβ), contribute to the activation of fibroblasts, which in turn secrete IGF2." (PMID 36672737, 2023). "Excessive IGF2 expression has often been observed in tumor patients." (PMID 38068544, 2023). "Consequently, IR can mediate primary resistance to IGF-1R target therapy, as IR overexpression leads to elevated levels of IR-A, which binds IGF-2 with high affinity, promoting tumor development." (PMID 37834454, 2023). "Of note, the role of mouse strain on RT2 tumor formation has also been monitored, and the strain of mouse can either alter the rate of tumor formation or favor other pNEN subtypes, including creating NF pNENs, dependent on expression of genes including Insm1 and IGF2." (PMID 37568572, 2023). "Moreover, IR-A activated by IGF-2 promotes metastasis and tumor progression, which is highly correlated with hormone-resistant breast cancer." (PMID 35207564, 2022). "Besides, the expression of VEGF (Mhigh/Mlow = 1.48 fold, p-Value = 0.021), NGF (Mhigh/Mlow = 1.79 fold, p-Value = 0.005), and IGF2 (Mhigh/Mlow = 2.12 fold, p-Value = 0.014), which were involved in tumor metastasis were also increased in the Mhigh group." (PMID 35740540, 2022). "In conclusion, the overexpression of IGF-2 may lead to severe growth and development disorders in both the embryonic period and the adult period and can even lead to tumor growth." (PMID 36358907, 2022). "IGF2R expression was consistent with the expression pattern of these biomarkers, suggesting that IGF2R may potentially promote tumor EMT via the IGF2/IGF2R signaling pathway." (PMID 36299463, 2022). "A monoclonal antibody against IGF-1R, AMG-479, and its kinase inhibitor, MK0406, effectively inhibit the proliferation of ovarian tumor cells and enhance tumor sensitivity to chemotherapeutic drugs such as cisplatin and taxane, which indicates that IGF-2 is an effective target for cancer therapy." (PMID 36358907, 2022). "In the present study, double deletion of Igf2 and Srsf3 (DKO mice) prevents hepatic fibrosis and inflammation, and completely prevents tumor formation, and is associated with decreased proliferation, apoptosis and DNA damage, and restored DNA repair enzyme expression." (PMID 35615981, 2022).
tumor (continued). "Some studies have indicated that IGFBP-6 could inhibit tumor angiogenesis in multiple systems through the IGF-2-independent pathway." (PMID 36193073, 2022). "We cannot exclude that IGF2, the second IR-A ligand, might contribute to the faster tumor growth and metastasis in animals inoculated with 4T1/IR-A cells when compared to 4T1/IR-B cells." (PMID 34831367, 2021). "Compared with short-term rhGH, long-acting PEG-rhGH did not significantly increase tumor-associated IGF-2 and IGFBP-2 expressions." (PMID 34899612, 2021). "The upregulation of IGF2 has been widely observed in many types of human tumors and could be a potential driver in carcinogenesis and tumor metastasis." (PMID 33407516, 2021). "Evaluation of raw gene transcripts per million for key upregulated genes with strong upregulation in tumor and PDX, and prior reported involvement in HB, including GPC3, DLK1, and IGF2, showed robust increase in HB tumor gene expression with further elevated expression in PDX tumors." (PMID 34497364, 2021). "Since IGF2 is upregulated by LOI in a high percentage of patients, and can also cause I-NETs to form in mice, IGF2 is the first gene that fits the strict criteria of a tumor driver gene in I-NETs." (PMID 34680217, 2021). "In addition, the family of RNA-binding proteins insulin-like growth factor 2 mRNA-binding proteins (IGF2BP1, 2, 3) regulates IGF2 transcript stability at post transcriptional level by modulating IGF2 production in embryos and tumor cells." (PMID 34440844, 2021). "Indeed, GPC-3 binding to growth factors such as IGF-2 in different tumor cell types affects these cells’ survival, as GPC3 can induce apoptosis or inhibit proliferation in a cell line-specific manner, and these cells can be rescued by IGF-2 signaling." (PMID 34069554, 2021). "The availability of organoids and spheroids may finally allow the study of downstream targets of somatostatin and IGF2 in I-NETs as well as the importance of candidate tumor genes like MIR1-2, RASSF1A, APC, or CDKN1B." (PMID 34680217, 2021). "In that cancer model, the circRNA/IGF2/Akt axis induced increased expression of the mRNA and protein for glutaminase, an enzyme that converts glutamine to glutamate, which is a major carbon source for ATP production in tumor cells." (PMID 33673232, 2021). "In addition, there are some studies that suggest that IGF2 is an important tissue marker for tumor progression in patients with liver metastases from CRC." (PMID 34422629, 2021). "Interestingly, LOI of IGF2 was also observed in matched normal tissue from these patients, including, in some cases, in normal tissue cut >20 cm from the tumor itself." (PMID 34680217, 2021). "Treatment of tumor cells with isiPI3K upregulated transcript levels of IGF2 in both cell lines." (PMID 34067117, 2021). "Interestingly, IGF2 mRNAs are directly regulated by IGF2BP2 in those embryonal cells, thereby suggesting a putative post-transcriptional mechanism of IGF2 dysregulation in this tumor." (PMID 34440844, 2021). "CAFs and tumor cells need reciprocal communication to stimulate mediators such as vimentin, matrix metalloproteinase (MMPs); periostin; Insulin growth factor-2 (IGF2); IL-33; and CXCL12, related to and tumor growth, invasion, and downregulation of tumor suppressor genes." (PMID 34204259, 2021). "Interestingly, the tumor promotion effect of biallelic Igf2 expression only happened in female mice." (PMID 34539876, 2021). "Indeed, it had a role in sponging miR-665, thus determining tumor growth due to the up-regulation of the miR target insulin-like growth factor 2 (IGF2)." (PMID 33477833, 2021). "IGF2 expression boosts cancer cell survival and tumor progression in colon cancer." (PMID 32427884, 2020). "Big IGF2 (11–18kDA) was detected only in the pre-operative serum and tumor samples." (PMID 32393233, 2020). "IGF2 deregulation determines overgrowth and region-specific tumor development in BWS." (PMID 33101381, 2020).
tumor (continued). "Interestingly, miR-491 was recently reported to act as a tumor-suppressive microRNA by inhibiting the known IGF2BP targets IGF2 and HMGA2." (PMID 32545414, 2020). "Similarly, IGF-2-secreting CAFs promote tumor regrowth and decreased latency after primary resection in CRC." (PMID 33553157, 2020). "In addition, the dysregulation of IGF2 expression has been recently observed also in several tumor onsets such as for breast, ovarian, esophageal, and colorectal cancer, and its presence has been reported and associated with poor prognosis." (PMID 33101381, 2020). "In this tumor, negative modulation of the CDX2/miR-615-5p/IGF2 axis was associated with increased tumor size and weight in animal models, as well as increased expression of tumor progression markers such as Ki-67, cyclin D1, c-MYC and Bcl-2." (PMID 32605009, 2020). "Thus, we designed this study to determine if differentially methylated regions of the IGF2 gene correspond to IGF2 protein expression in paired (Normal/Tumor) breast tissues and in BC cell lines." (PMID 33216823, 2020). "By the way, studies showed that IGF2 could preserve tumor cell survival by creating an autophagic state of dormancy." (PMID 33173015, 2020). "There is, however, a paucity of literature demonstrating whether big IGF-2 exerts the tumor growth effect in an endocrine manner." (PMID 32993631, 2020). "Taken together, our results suggest that IGF-2 expression may be a potential useful marker of tumor aggressiveness and poor prognosis in luminal tumors." (PMID 33114046, 2020). "This receptor is considered a tumor suppressor, as both the ligand and receptor are internalized and degraded after binding, reducing the bioavailability of IGF2 and, thus, inhibiting the proliferative effects of IGF2." (PMID 33260481, 2020). "The tumor development in H19/IGF2:IG-DMR -GOM cases is significantly higher compared to UPD cases." (PMID 33101381, 2020). "In contrast, IGF1 expression does not significantly change between the considered conditions, and IGF2 expression tends to decrease in primary tumours compared to normal tissue (p = 0.05) and significantly increases in metastatic samples compared to primary tumours (p = 0.0036)." (PMID 32385236, 2020). "Thus, IGF-2 contributes to the creation of the optimal tumor microenvironment, which provides it with the transport of factors necessary for growth." (PMID 32850012, 2020). "The IGF2 mRNA-binding protein 1 (IGF2BP1) is a non-catalytic post-transcriptional enhancer of tumor growth upregulated and associated with adverse prognosis in solid cancers." (PMID 32761127, 2020). "As IMP family members and IGF2 are critical in promoting cell proliferation, they maintain stem cell stemness under physiological conditions, but are also thought to favor cancer cell progression in diverse tumor types along with their high expression." (PMID 31484925, 2019). "Many of these targets function as oncogenes or tumor growth indicators, such as insulin-like growth factor 2 (IGF-2), a crucial growth and differentiation factor for muscle tissues, and IGF-2 mRNA-binding protein 2, which binds several mRNAs encoding mitochondrial respiratory chain complex subunits." (PMID 30976203, 2019). "Disappointingly, clinical trials employing these agents showed modest reductions in tumor growth as multiple resistance mechanisms (an IGF2/IRA autocrine signaling loop or rising levels of circulating IGF-IR that sequesters IGF-IR inhibitors) quickly overcame their IGF-IR inhibition." (PMID 31269742, 2019). "Hence, the concept of direct autocrine/paracrine tumor cell activation through IGF2 is supported by this study." (PMID 31623387, 2019). "An artificial endocrine pancreas may have the potential to stabilize the intraoperative blood glucose change in insulin-like growth factor 2-releasing tumor resection." (PMID 32025979, 2019). "IGF2 immunostaining was also observed in normal liver adjacent to tumor masses." (PMID 31623387, 2019).
tumor (continued). "Importantly, IGF2 produced by CAFs also induced autophagy in cancer cells, indicating a feed‐forward loop to promote autophagy in the tumor microenvironment." (PMID 30302772, 2019). "In PCa, IGF2 seems to be particularly important during early phases of tumorigenesis, or when an advanced tumor is challenged through chemotherapy or androgen deprivation, while it may be less relevant in established tumors under ‘steady‐state’ conditions." (PMID 29239100, 2018). "We wondered whether IGF-1 and IGF-2 might also be expressed in the metastatic tumor microenvironment and thereby provide a survival/proliferative signal to disseminated cancer cells." (PMID 29367764, 2018). "IGF2 had normal monoallelic expression in both tumours (37T and W117)." (PMID 29912901, 2018). "Together, these observations could indicate that the relative importance of IGF2 may vary during different stages of a tumor." (PMID 29239100, 2018). "On the basis of our findings, we propose that GBM tumor growth is characterized by a structured population with less aggressive clones (TMZ-sensitive-IGFBP6+-IFG-1R−) that block the expansion of more aggressive cells (TMZ-resistant-IGF2+IGF-1R+)." (PMID 30231881, 2018). "In line with observations in other tumor entities, the reduced expression of IGF2 in most PCa compared to normal prostate correlated well with P3 and P4 hypermethylation and with downregulation of the respective IGF2 transcripts." (PMID 29239100, 2018). "For instance, EGF plays an important role in tumour proliferation and metastasis; PDGFβ induces liver fibrosis and accelerates tumour development; VEGFA is one of the major growth factors responsible for angiogenesis; and IGF2 enhances tumour cell proliferation." (PMID 29346427, 2018). "We conclude that IGF2 is downregulated in most PCa and may be particularly relevant during early stages of tumor development or during chemotherapy and androgen deprivation." (PMID 29239100, 2018). "Several lines of evidence suggested that IGF‐2 signaling is required for MSC tumor tropism." (PMID 29321953, 2018). "The increased tumor expression of IGF2 observed in black women with UCS may reflect differences in DNA methylation at its regulatory sites." (PMID 29455465, 2018). "The present results indicate that the tumor co-expressed IGF2 and IGF2R." (PMID 30168002, 2018). "In addition, the tumor cells exhibited cytoplasmic IGF2 expression, specifically with paranuclear dot-like reactivity." (PMID 30168002, 2018). "The interference of FGF-2 with HPSE as well as TGF-β and IGF-2 for CD222 activity in the tumor microenvironments may modulate epithelial-mesenchymal interactions." (PMID 30333909, 2018). "The relationship between IGF2 expression and tumor grade is unclear." (PMID 30168002, 2018). "Next, we examined the possible involvement of IGF‐2 secreted by tumor cells in recruiting MSCs." (PMID 29321953, 2018). "Unlike IGF-1, IGF-2 is an epigenetically regulated gene mainly involved in fetal development and expressed by both alleles only in early tumor cells, which suggests that IGF-2 plays a critical role in oncogenesis." (PMID 30111747, 2018). "Nevertheless, IGF2 murine transgenic models have highlighted features close to the BWS without tumor predisposition." (PMID 29867024, 2018). "However, activation of IGF2 stimulates the proliferation of tumor cells and prevents damaged cells from being destroyed." (PMID 30778372, 2018). "In the present study, we examined whether Id1-induced IGF2 plays any role in tumour angiogenesis and whether it exerts paracrine effects in the tumour microenvironment and tumour macroenvironment to further facilitate cancer progression." (PMID 28186102, 2017).